KL (klotho)
Diseases named in the same sentence as KL in open-access papers (continued):
Sharing a sentence is not in itself a finding about the gene and the disease.
type 2 diabetes (continued). "However, few studies have investigated the association of fibroblast growth factor 23 (FGF23), α-klotho and FGF23/α-klotho ratio with atherosclerosis in patients with type 2 diabetes mellitus (T2DM)." (PMID 38622690, 2024). "We have previously demonstrated in individuals with type 2 diabetes and MA+ that RAS inhibition increases soluble Klotho levels." (PMID 28194484, 2017). "Previous data indicate that soluble Klotho levels are not affected in type 2 diabetes patients with and without the macrovascular disease." (PMID 35053218, 2022). "Zhang and Liu reported that both alpha and beta Klotho levels were lower in patients with type 2 diabetes, and correlated with fructosamine, but not with HbA1c." (PMID 34603200, 2021). "The role of the KLOTHO gene in type 2 diabetes is not known." (PMID 16753056, 2006). "Serum soluble Klotho (sKlotho) levels exhibit a significant negative correlation with varying degrees of urine albumin in patients with type 2 diabetes mellitus(T2DM)." (PMID 37859992, 2023).
left ventricular hypertrophy (33 papers, 2013 to 2026). Enlargement of the LEFT VENTRICLE of the heart. "Using aged and Klotho-deficient mouse models, they demonstrated that soluble Klotho (sKL) supplementation improved cardiac diastolic function, reduced left ventricular hypertrophy and fibrosis, and increased capillary density." (PMID 40894259, 2025). "The researchers utilized wild-type and heterozygous Klotho-deficient mice to access the effects of 10 weeks of sKL supplementation on left ventricular hypertrophy (LVH), diastolic dysfunction, and other age-related cardiac phenotypes." (PMID 40894259, 2025). "Klotho-deficient CKD mice have significant left ventricular hypertrophy (LVH) and cardiac fibrosis compared with wild-type mice." (PMID 32545510, 2020). "For example, in the heart, FGF23 might cause left ventricular hypertrophy in a klotho‐independent manner via FGFR4." (PMID 38050660, 2024). "Treatment with Klotho protein in a CKD-related left ventricular hypertrophy mouse model significantly inhibited the development of left ventricular hypertrophy." (PMID 39931238, 2025). "In human patients with CKD-related left ventricular hypertrophy (LVH), elevated left ventricular mass was related to lower serum Klotho, and the presence of Klotho caused the inhibition of cardiomyocyte hypertrophy induced by uremic toxins in vitro." (PMID 38787156, 2024). "Klotho efficiently suppressed NOX2/4 and ROS overproduction in hypertrophic neonatal rat cardiomyocytes and heart tissue in CKD-associated left ventricular hypertrophy mouse model." (PMID 37985893, 2023). "The prevalence of left ventricular hypertrophy and vascular calcification was higher in the low Klotho/FGF23 ratio quartiles at baseline and at the fourth-year follow-up." (PMID 35872753, 2022). "CKD is a state of Klotho depletion, and low levels of circulating Klotho associate with relatively reduced FMD and thicker carotid intima in healthy subjects and with arterial stiffness and left ventricular hypertrophy in CKD patients." (PMID 32718053, 2020). "Low klotho levels are associated with increased oxidative stress, inflammation, and accelerated aging-like phenotypes, while elevated FGF-23 independently predicts left ventricular hypertrophy and mortality in CKD patients." (PMID 40002748, 2025). "Our group also showed that umbilical cord Klotho levels were depressed in infants with bronchopulmonary dysplasia (BPD) and pulmonary hypertension and that Klotho administration improved pulmonary hypertension, left ventricular hypertrophy and cardiac dysfunction in the same hyperoxia rat model." (PMID 35844742, 2022). "FGF23 is associated with left ventricular hypertrophy (LVH) in CKD and induces LVH via klotho-independent FGFR4-mediated activation of calcineurin/nuclear factor of activated T cells (NFAT) signaling in animal models, displaying systemic alterations possibly contributing to heart injury." (PMID 34778257, 2021). "For this reason, Klotho protein may initiate the new preventive and therapeutic strategy in left ventricular hypertrophy." (PMID 30671457, 2018). "In addition, FGF23 may contribute to left ventricular hypertrophy by a direct, Klotho‐independent action on cardiomyocytes." (PMID 25858796, 2015). "Indeed, FGF23 may contribute to pathological left ventricular hypertrophy in a Klotho-independent manner." (PMID 24348262, 2013). "The hormonal effects of circulating klotho protein and FGF23 on the vascular and heart have contributed to arterial stiffness and left ventricular hypertrophy." (PMID 37334749, 2023). "Hyperphosphatemia leads to a depletion of Klotho levels and increased FGF-23 levels, both of which directly contribute to left-ventricular hypertrophy followed by cardiac fibrosis and coronary calcification." (PMID 38255650, 2023).
left ventricular hypertrophy (continued). "Investigation of the interaction between Klotho and the uremic toxin indoxyl sulfate (IS) in CKD-associated left ventricular hypertrophy (LVH) revealed a negative correlation between serum levels of IS and Klotho and both IS and Klotho levels were independently associated with LVH." (PMID 40799848, 2024). "While it was reported that FGF23 signals in a Klotho-independent fashion through FGFR4/nuclear factor of activated T cells/calcineurin, which may cause left ventricular hypertrophy, it has not been shown how FGF23 can activate FGF receptor without Klotho." (PMID 29515522, 2018). "Furthermore, intramyocardial administration of FGF23 resulted in left ventricular hypertrophy in the absence of klotho." (PMID 28870151, 2017). "Increased hemoglobin values favor myocyte oxygenation, while Klotho preservation prevents the negative consequences of Klotho deficiency, which reproduces the cardiovascular phenotype of CKD: cardiovascular calcification, hyperaldosteronism, left ventricular hypertrophy, and myocardial fibrosis." (PMID 40563333, 2025). "In the heart, FGF-23 induces left ventricular hypertrophy independent of its co-factor, klotho, and in vascular smooth muscle cells, FGF23 inhibits vascular calcification, an effect that is klotho-dependent." (PMID 24019880, 2013).
coronary artery disease (31 papers, 2005 to 2025). "Clinical trials showed that adults with high level of plasma Klotho have lower risk of coronary artery disease (CAD), heart failure, stroke, and peripheral arterial disease (PAD)." (PMID 36077539, 2022). "In a previous study which dealt with Klotho and vascular surrogate markers or cardiovascular outcome, low level of Klotho was found to be associated with the presence and severity of coronary artery disease." (PMID 31398214, 2019). "In previous works, our group reported that low vascular KL gene expression was associated with the presence and severity of coronary artery disease and clinical atherosclerotic disease independently of established cardiovascular risk factors." (PMID 30987161, 2019). "Clinical studies have also shown that serum klotho levels are inversely associated with the severity of coronary artery disease in patients with normal kidney function and abdominal aortic calcification (AAC) undergoing MHD." (PMID 30314461, 2018). "Moreover, in stark contrast to the present study, a research conducted in China reported the TT genotype of Klotho C1818T as a susceptibility factor for coronary heart disease." (PMID 30547758, 2018). "On the other hand, in patients with significant coronary artery disease, both serum and coronary wall klotho mRNA levels are notably reduced, and this reduction correlates independently with disease severity." (PMID 38610757, 2024). "In this work, the relationship between Klotho levels and the coronary artery disease (CAD) burden in subjects with T2DM and preserved kidney function was analyzed." (PMID 37686263, 2023). "This work concluded that patients with significant coronary heart disease presented lower soluble concentrations of Klotho, as well as reduced levels of Klotho expression in thoracic aorta." (PMID 26538295, 2016). "In the present work, vascular Klotho mRNA levels were significantly lower in subjects with coronary artery disease, and interestingly the presence of allele A variant of the G‐395A Klotho gene polymorphism was associated with lower vascular Klotho expression." (PMID 26538295, 2016). "A second gene related to premature aging in man and in murine models is the KLOTHO gene, a hypomorphic variant of which (KL-VS) is significantly more common in the first-degree relatives of patients with premature coronary artery disease (CAD)." (PMID 16262891, 2005). "The findings of the present work suggest that variability of Klotho genotype may be related to vascular Klotho expression and coronary artery disease." (PMID 26538295, 2016). "Therefore, the analysis of the associations of FGF23 with coronary disease should be done separately from those patients with CKD, even with a minor impairment, since the decrease of Klotho expression is an early event in CKD." (PMID 22590632, 2012). "In terms of clinical coronary disease, patients had lower soluble serum Klotho levels, which indicated a significant negative correlation with the severity of coronary stenosis." (PMID 32138681, 2020). "Our results suggest that serum Klotho is higher in individuals with a clinical history of myocardial infarction but not with a history of coronary artery disease or stroke." (PMID 28076518, 2016). "We hypothesized that common variation at the LMNA or KLOTHO loci might result in typical forms of coronary disease in the absence of progeroid syndromes." (PMID 16262891, 2005).
Insulin resistance (31 papers, 2007 to 2025). Increased resistance towards insulin, that is, diminished effectiveness of insulin in reducing blood glucose levels. "While it has been reported that α-Klotho is downregulated in patients with insulin resistance (IR), the association between Klotho and IR is complex and controversial." (PMID 38907289, 2024). "Conversely, Klotho loss-of-function mutant mice display impaired glucose tolerance and insulin resistance." (PMID 38501099, 2024). "By inhibiting NLRP3-inflammasome activation, Klotho prevents maturation of the proinflammatory cytokines IL-1β and IL-18, cell death, and the loss of pancreatic islet mass and lowers insulin resistance." (PMID 33478014, 2021). "We analyzed the role of FGF19, FGF21 and Klotho protein in children with normal body weight as well as in overweight and obese subjects and explored their associations with insulin resistance (IR) and metabolic syndrome (MS) and its components." (PMID 32546231, 2020). "Therefore, the inhibition of TLR4 by Klotho contributes to the protection of tissues against inflammation-associated injury and insulin-resistance, especially because TLR4 is involved in generating oxidative stress." (PMID 33478014, 2021). "Because klotho is reportedly associated with insulin resistance, the association between FGF23 and resistin could potentially result from the effects of klotho." (PMID 30228288, 2018). "On the one hand insulin resistance is associated with a series of fatal disorders and centenarians are known to have high insulin sensitivity, but on the other, the Klotho gene whose overexpression is known to increase lifespan has been shown to act by increasing insulin resistance." (PMID 17437648, 2007). "Klotho seems to interfere with insulin receptor signaling and downstream processes, contributing to muscle wasting and insulin resistance [31▪,32▪,33]." (PMID 40237064, 2025). "Deregulated FGF23 and klotho are involved in impaired insulin signaling and insulin resistance through various potential mechanisms." (PMID 40237064, 2025). "Some organokines have protective effects (e.g., FGF-21, irisin, and klotho), while others, such as myostatin and fetuin-A, exacerbate insulin resistance and fibrosis." (PMID 41373697, 2025). "The findings align with emerging preclinical evidence indicating neuroprotective properties of klotho against neuronal insulin resistance and oxidative stress." (PMID 38505757, 2024). "Recent studies have elucidated the role of Klotho, a protein expressed in various tissues, including the placenta, in exacerbating insulin resistance, particularly in GD." (PMID 39519193, 2024). "The dysregulation of the mTOR pathway and the overexpression of Klotho protein contribute to persistent hyperglycemia and insulin resistance." (PMID 39519193, 2024). "Other researchers have shown that Klotho expression exhibits an inverse relationship with various aspects of lipid metabolism, such as inflammation, oxidative stress, and insulin resistance." (PMID 38027194, 2023). "Klotho induced insulin resistance in adipocytes by regulation of glucose transporter type 4 and intracellular insulin signalling through AKT43." (PMID 37985893, 2023). "Low levels of soluble Klotho have been shown in mouse studies to induce insulin resistance and to increase hepatic gluconeogenesis and hepatocyte lipid accumulation in T2D." (PMID 36797683, 2023). "In a word, the results of this study showed that silencing of klotho reversed the decrease of cell activity induced by HG and alleviated insulin resistance." (PMID 36325267, 2022). "Thiazolidinedione pioglitazone (designed to reduce insulin resistance by increasing peripheral glucose disposal and decreasing glucose production) resulted in increased expression of Klotho and protection against renal injury in aging." (PMID 32982966, 2020).
Insulin resistance (continued). "Recent studies have shown that S-klotho production is downregulated in persons with diabetes mellitus type II; such patients experience hyperglycaemia, insulin resistance and an attenuated resistance to oxidative stress." (PMID 31390595, 2019). "Two lines of Klotho Tg mice also showed reduced fecundity in females and insulin resistance in both genders." (PMID 21876806, 2011). "Klotho gene induced insulin resistance is shown to increase longevity but lipo-apoptosis, inflammatory changes and beta cell defects are the confounding factors leading to the cluster of diseases." (PMID 17437648, 2007). "The potential mechanism by which Klotho negatively correlates with hyperlipidemia might involve anti-inflammatory effects, insulin resistance, and antioxidants." (PMID 41140975, 2025). "This insulin resistance is exacerbated by the overexpression of Klotho." (PMID 39519193, 2024). "Targeting the mTOR pathway and Klotho protein overexpression could also provide novel strategies to manage hyperglycemia and insulin resistance in GD." (PMID 39519193, 2024). "In the review of the literature, one hypothesis suggested that in subjected overnutrition, the Klotho protein may induce insulin resistance to oppose the life-shortening consequences of lipotoxicity and lipoapoptosis." (PMID 35053218, 2022). "On the other side, klotho might induce insulin resistance in adipocytes, preventing insulin effects on promotion of GLUT4 plasma membrane translocation, and attenuating intracellular insulin signalling through main mediators, such as Akt, GSK3β, and PFKf3β." (PMID 35279809, 2022). "Reduced blood Klotho concentration is associated with increased albuminuria.Klotho levels were correlated with FGF23, vitamin D, and insulin resistance, suggesting that Klotho levels might be affected by renal function." (PMID 35626360, 2022). "Insulin resistance induced by Klotho gene over-expression is accompanied by reduced adiposity." (PMID 17437648, 2007). "Additionally, it has been discovered that silencing Klotho in high glucose-treated cells increased IGF1R, p-IGF1R and IGF1 expression, and activates the IGF1/PI3K/Akt/mTOR signalling pathway, known to be associated with insulin resistance." (PMID 38486352, 2024). "Klotho-mediated insulin resistance may function as a mechanism to counteract the aging process." (PMID 38907289, 2024). "Consequently, we hypothesized that the potential mechanism by which Klotho negatively correlates with hyperlipidemia might involve anti-inflammatory effects, insulin resistance, and antioxidants." (PMID 38027194, 2023). "While some (such as FGF-21, irisin, adiponectin, klotho, and osteocalcin) have protective effects, others (such as myostatin, fetuin-A, visfatin, and ANGPTL3) exacerbate insulin resistance, inflammation, and fibrosis." (PMID 41373697, 2025). "Klotho inhibits signals of insulin/IGF-1 receptors (IR/IGF-Rs), and insulin receptor substrate 1 (IRS1), and induces insulin resistance." (PMID 27861640, 2016). "Therefore, Klotho may inhibit HDL transformation through insulin resistance." (PMID 27861640, 2016). "However, unlike FGF21, Klotho causes insulin resistance, which may limit its utility as a therapeutic agent." (PMID 23066506, 2012). "In addition, the recent discovery of a hormone associated with longevity called 'klotho' that can induce insulin resistance and upregulate FOXO is therefore significant, as is supports the observation that the right degree of insulin resistance may aid long-term survival." (PMID 17531095, 2007). "When the soluble Klotho protein was intraperitoneally administered to wild-type mice, the insulin and IGF-1 sensitivity of the mice was impaired, indicating that increased Klotho protein in the blood induced insulin resistance, as well as IGF-1 resistance." (PMID 21876806, 2011). "Klotho may affect HDL-C and LDL-C levels through insulin resistance." (PMID 27861640, 2016).